GATA4 (GATA binding protein 4)
Diseases named in the same sentence as GATA4 in open-access papers (continued):
Sharing a sentence is not in itself a finding about the gene and the disease.
cryptorchidism (4 papers, 2018 to 2023). The failure of one or both testes of a male fetus to descend from the abdomen into the scrotum during the late part of pregnancy. "Remarkably, the patients’ mother presenting with a mitral valve prolapse, and his maternal uncle having a similar history of micropenis and cryptorchidism, were both carriers of the same heterozygous GATA4 variant." (PMID 29670578, 2018).
diaphragmatic hernia (4 papers, 2013 to 2026). A congenital or acquired weakness or opening in the diaphragm which allows abdominal contents to protrude into the chest cavity; congenital diaphragmatic hernias are caused when the embryonic diaphragm fails to fuse. "The report presents a detailed clinical description of the fetus with ultrasound, MRI, and post-mortem pictures of a rare prenatal isolated diaphragmatic hernia related to a novel pathogenic GATA4 sequence variant." (PMID 41099604, 2026). "Gata4+/Δex2 mice, which harbor a deletion in exon 2 of Gata4, have anterior congenital diaphragmatic hernias that are similar to those seen in FREM1-deficient mice." (PMID 23536828, 2013). "Haploinsufficiency of GATA4 is also associated with diaphragmatic hernia." (PMID 41099604, 2026). "The fact that Fat1 deficiency did not alter diaphragm development or lead to diaphragmatic hernias such as those occurring in the absence of Gata4 make it unlikely for Fat1 to be required in the Gata4+/diaphragm CT subtype." (PMID 29768404, 2018).
gastric adenocarcinoma (4 papers, 2017 to 2022). "In genomics, ERBB2, VEGFA, GATA4 and GATA6 gene amplifications were frequently observed in Barrett’s adenocarcinomas, which strongly resemble the chromosomally unstable variant of gastric adenocarcinoma." (PMID 33087057, 2020). "Of these, 8 regions contained previously characterized amplified oncogenes: GATA4, CCND1, CDK6, MDM2, EGFR, MCL1, ERBB3 and MYB; this is the first report of significant and nearly isolated MYB amplification in gastric adenocarcinoma." (PMID 28426752, 2017).
Hepatic steatosis (4 papers, 2012 to 2025). Steatosis is a term used to denote lipid accumulation within hepatocytes. "In the present study, we have investigated the effect of intestinal GATA4 deficiency on hepatic steatosis and fibrosis." (PMID 22750465, 2012). "Our results provide strong indications for a protective effect of intestinal GATA4 deficiency on the development of hepatic steatosis and fibrosis via GLP-1, thereby blocking hepatic de novo lipogenesis." (PMID 22750465, 2012). "For example, intestine-specific knockout of the zinc finger transcription factor GATA4 reduces intestinal lipid absorption and was protective against hepatic steatosis induced by feeding a high fat but not MCD diet." (PMID 32158763, 2020).
infarction (4 papers, 2017 to 2025). A localised pathological necrosis of tissue resulting from obstruction of the blood supply usually by a thrombus, an embolus, or vascular torsion. "In the present study, exosomes isolated from GATA-4-expressing BMSCs improved cardiac function as well as tissue integrity when injected 48 h after initiation of infarction in mice." (PMID 29899566, 2018). "Exosomes isolated from GATA-4-expressing BMSCs induce differentiation of BMSCs into cardiomyocyte-like cells, decrease anoxia-induced cardiomyocyte apoptosis, and improve myocardial function after infarction." (PMID 29899566, 2018). "At 14–21 days after infarction and cell delivery, considerable areas of the infarcted LV were replaced by small fluorescently labeled cells, expressing α-sarcomeric actin (α-SA) and GATA4." (PMID 29302361, 2017). "The difference between our study and those studies in which both GATA-4-exosomes and control exosomes improved post-infarction ventricular function may be due to the timing of the exosome injections (i.e., at the beginning of infarction versus at 48 h after infarction)." (PMID 29899566, 2018).
ischemia (4 papers, 2017 to 2026). A hypoperfusion of the BLOOD through an organ or tissue caused by a PATHOLOGIC CONSTRICTION or obstruction of its BLOOD VESSELS, or an absence of BLOOD CIRCULATION. "As demonstrated, GATA4 was activated by β1-AR up-regulation through cAMP-PKA signaling pathway in early phase of ischemia, then GATA4 positively regulated let-7a expression which in turn suppressed β1-AR expression." (PMID 28060734, 2017). "This can be translated into a more physiological term: in the early stage, or the acute phase, of ischemia, the enhanced sympathetic tone induces β1-AR activation and the subsequent signal transduction, leading to activation of GATA4 thereby the expression of let-7a." (PMID 28060734, 2017).
leukemia (4 papers, 2015 to 2025). A malignant (clonal) hematologic disorder, involving hematopoietic stem cells and characterized by the presence of primitive or atypical myeloid or lymphoid cells in the bone marrow and the blood. "However, further research focusing on the molecular mechanism underlying the role of GATA4 in pediatric leukemia is required." (PMID 26490736, 2015). "Previously, GATA4 has been proven to regulate the proliferation capability of a variety of cell types, such as cardiomyocytes, small intestinal epithelial cells, follicular granulosa cells, and leukemia lymphocytes." (PMID 34545275, 2021). "However, further research focusing on the mechanism of GATA4 in pediatric leukemia is required." (PMID 26490736, 2015).
liver cancer (4 papers, 2016 to 2022). An epithelial or non-epithelial malignant neoplasm that arises from the liver. "We reasoned that deficiency of GATA4 in liver cancer cells unleashed the oncogenic activity of β-catenin." (PMID 31903133, 2020). "Hepatocyte-specific Gata4-KO mice developed enlarged livers with a proliferative precursor phenotype, thus play a role in liver cancer development." (PMID 35327967, 2022). "The results showed that regardless of the patient's HBV and HBsAg status, the expression level of GATA4 decreased in liver cancer tissues of most patients." (PMID 34583732, 2021). "Reflecting the involvement of this module in liver cancer patients, we observed that frequency of CTNNB1 mutation tend to be higher in GATA4-low patients than in GATA4-high cohorts." (PMID 31903133, 2020). "This module functions to not only prevent β-catenin from transcribing canonical Wnt signaling target genes to support liver cancer cell growth, but also recruit β-catenin to facilitate transcription of TSGs by GATA4 in HCC cells." (PMID 31903133, 2020). "Of note, we observed similar trend of inhibitory function of GATA4 on mutant β-catenin frequently seen in liver cancer patients such as S45Y." (PMID 31903133, 2020). "Taken together, these in vitro data strongly argued that GATA4 was a potent TSG for liver cancer." (PMID 31903133, 2020). "We re-analyzed our RNA-seq data and found several liver cancer TSGs among GATA4-upregulated genes." (PMID 31903133, 2020). "We went on to check whether GATA4 interacted with β-catenin in nuclei of liver cancer cells." (PMID 31903133, 2020). "For this purpose, we checked GATA4 expression level in liver cancer cell lines commonly used in cancer research community through western analysis, including two pairs of HCC/para-tumoral tissues as references for GATA4 expression in tumoral and normal liver tissues." (PMID 31903133, 2020).
lung adenocarcinoma (4 papers, 2017 to 2022). A carcinoma that arises from the lung and is characterized by the presence of malignant glandular epithelial cells. "In addition, the mutation rates of GATA4 in lung adenocarcinoma and squamous cell lung carcinoma were 10% and 12%, respectively, which were both the highest mutation rates compared with other GATAs and the deep deletion accounted for most changes." (PMID 34093794, 2021). "The increased GATA2/3/5/6 mRNA levels and the decreased GATA4 mRNA levels in lung adenocarcinoma were remarkably related to improved OS." (PMID 34093794, 2021). "Among them, the alteration rates of GATA4/5/6 were 10, 10, and 8%, respectively in lung adenocarcinoma." (PMID 34093794, 2021). "At least one copy of GATA4/8p is deleted in 51% of lung adenocarcinoma tumors." (PMID 35017504, 2022). "In order to find supporting evidence in clinical samples for our model, we searched the expression data for GATA4, TGFB2, and WNT7B in lung adenocarcinoma patients from The Cancer Genome Atlas (TCGA)." (PMID 30971692, 2019). "Gata4 expression serves as a potent tumor-suppressive mechanism in an autochthonous model of Kras-driven lung adenocarcinoma, affecting tumor initiation, but not cell proliferation." (PMID 35017504, 2022). "To investigate whether the tumor-suppressive effects of Gata4 are cell-autonomous or non-cell-autonomous, we mixed KP lung adenocarcinoma cells containing either tet-Gata4 or tet-GFP." (PMID 35017504, 2022).
prostate carcinoma (4 papers, 2018 to 2021). A carcinoma that arises from epithelial cells of the prostate gland. "We also identified groups that contained validated prostate cancer oncogenes with novel associations, such as SOX4, a prostate cancer transforming oncogene, and FOXA2 and GATA4, known pioneer factors (oTFCG13)." (PMID 30314329, 2018). "Strikingly, prostate cancer patients receiving anti-androgen therapy exhibited a significant decrease in the levels of testicular Rubicon and GATA4 relative to a tumor-free patient or prostate cancer patients who did not receive such treatment." (PMID 34351902, 2021). "Interestingly, two of the definitive subtype specific genes found by the TCGA were not expressed above background levels in any of the prostate cancer cell lines (PCOTH and GATA4)." (PMID 33303959, 2020).
rheumatoid arthritis (4 papers, 2018 to 2025). A chronic, systemic autoimmune disorder characterized by inflammation in the synovial membranes and articular surfaces. "GATA4 regulates angiogenesis and the persistence of inflammation in rheumatoid arthritis, according to a study." (PMID 37221510, 2023). "We find that a higher level of GATA4 exists in synovium of rheumatoid arthritis (RA) patients, but the function of GATA4 in RA remains unclear." (PMID 29717129, 2018). "GATA4 functioning in inflammation persistence and angiogenesis in rheumatoid arthritis (RA)." (PMID 33101015, 2020).
adrenal tumors (3 papers, 2010 to 2014). "Similar to observations made in most mouse adrenal tumour models, with age, adrenal glands of AdKO mice accumulated subcapsular Gata-4-positive spindle-shaped cells that are supposed to descend from multipotent progenitors capable to engage toward adrenal or gonadal fates." (PMID 20548949, 2010). "Unlike the reciprocal expression pattern of GATA4 and GATA6 in adrenal tumors, expression of GATA4 and GATA6 positively correlated with each other at both mRNA and protein levels in tumor and peritumor tissues (data not shown)." (PMID 24498120, 2014).
adrenocortical tumors (3 papers, 2010 to 2019). "In previous mouse models for adrenocortical tumours, the first signs of neoplastic transformation seemed to coincide with the emergence of Gata-4 positive cells growing centripetally from the subcapsular region." (PMID 20548949, 2010).
aortic valve stenosis (3 papers, 2012 to 2024). Aortic valve stenosis (AVS) is a condition characterized by narrowing of the heart's aortic valve opening. "By utilizing a mouse model harboring a human disease-causing mutation, we demonstrate a novel role for GATA4 in congenital semilunar valve stenosis." (PMID 31138536, 2019). "Our work is the first to mechanistically link a GATA4 human disease-causing mutation with congenital semilunar valve stenosis." (PMID 31138536, 2019). "In support of this, examination of a small number of mice heterozygous for the Gata4-null allele demonstrated a partially penetrant phenotype of aortic valve stenosis (data not shown)." (PMID 31138536, 2019). "This phenotype along with recent publications demonstrating bicuspid aortic valve and aortic valve stenosis in Gata5-null and Gata4;Gata5 compound heterozygote mice suggest that endocardial specific deficits of the G296S protein may contribute to the aortic and pulmonary valve stenosis." (PMID 22589735, 2012).
astrocytomas (3 papers, 2017 to 2023). "GATA4 has been found to be a tumor suppressor in astrocytomas." (PMID 36293188, 2022).
Cardiovascular malformations (3 papers, 2012 to 2022). "In fact, in GATA4/6 mutations carriers, particular in newborns, the evaluation and monitoring over time of congenital heart malformations and heart failure is mandatory." (PMID 35052457, 2022). "Cardiovascular malformations can be caused by abnormalities in Gata4 expression during fetal development." (PMID 25101666, 2014). "GATA4 heterozygous LOF mutations and complete deletion of the gene (deletion from 1 to 17 Mb that includes 8 additional genes), have been associated with congenital heart malformations, and more rarely with pancreatic agenesis and neonatal diabetes." (PMID 35052457, 2022).
cervical carcinoma (3 papers, 2012 to 2022). A carcinoma arising from either the exocervical squamous epithelium or the endocervical glandular epithelium. "Remarkably, GATA4 chromosome immunoprecipitation (ChIP) results revealed that GATA4-Gαi3 promoter DNA binding 33 in cervical cancer cells was robustly higher than that in priCEpi-1 and priCEpi-2 epithelial cells." (PMID 36263185, 2022). "Here in cervical cancer cells, Gαi3 was decreased following GATA4 shRNA, but was upregulated following GATA4 overexpression." (PMID 36263185, 2022). "GATA4 shRNA-expressing lentivirus 28 was stably transfected to primary human cervical cancer priCC-1 cells, resulting in robust GATA4 silencing." (PMID 36263185, 2022). "Significantly, an increased binding between GATA4 and Gαi3 promoter region in both cervical cancer tissues and various cervical cancer cells was detected." (PMID 36263185, 2022). "We therefore analyzed whether GATA4 was the primary mechanism of Gαi3 overexpression in cervical cancer." (PMID 36263185, 2022). "Abolishing GATA4 sumoylation by mutating the SUMO acceptor K365 or interfering with GATA4 sumoylation by knocking down the obligatory SUMO E2 conjugase, Ubc9, prevented GATA4 nuclear localization in HeLa cervical carcinoma cells." (PMID 22539995, 2012). "Therefore, GATA4 is indeed essential for Gαi3 expression in cervical cancer cells." (PMID 36263185, 2022). "In addition, promoter DNA methylation levels (average beta values) of ALDH1A2, GATA4, GRIA4, and IRX4 were significantly elevated in primary cervical carcinoma as compared to normal tissues." (PMID 34745985, 2021).
diabetic cardiomyopathy (3 papers, 2011 to 2023). Diabetic cardiomyopathy is a disorder of the heart muscle in people with diabetes. "Taken together, GATA-4 activation and nuclear translocation are important factors that lead to a reduction in cardiac contractility in diabetic cardiomyopathy." (PMID 21702924, 2011).
glioma (3 papers, 2021 to 2024). A benign or malignant brain and spinal cord tumor that arises from glial cells (astrocytes, oligodendrocytes, ependymal cells). "injected homologous glioma cells with high expression of GATA4 into nude mice and found that the control group with high expression of GATA4 survived with tumor-free, whereas the treatment group died of malignant glioma within 31 ± 7 days after injection." (PMID 34513713, 2021). "For instance, FOXQ1 and FOXF2 were highly expressed in glioma, FOXF1 in LUAD, and GATA4 in CHOL and LIHC, all consistent with previous studies." (PMID 39345334, 2024). "Some studies have reported that suppressed GATA4 and HOXA9 expression can inhibit malignancy and metastasis in glioma." (PMID 33503296, 2021).
left ventricular hypertrophy (3 papers, 2014 to 2021). Enlargement of the LEFT VENTRICLE of the heart. "Calcineurin regulated NFAT/GATA4 activation causes left ventricular hypertrophy in humans." (PMID 31211784, 2019). "Previous studies have found that p300 is required for acetylation and for the transcriptional activity of GATA4, as well as for pathological left ventricular hypertrophy and the development of HF in vivo." (PMID 33578969, 2021).
lung squamous cell carcinoma (3 papers, 2021 to 2022). "Based on TCGA (The Cancer Genome Atlas) one unknown alteration evidenced in our AFX cohort (GATA4 P359K) has been previously reported in lung squamous cell carcinoma." (PMID 34202213, 2021).
melanoma (3 papers, 2021 to 2025). A malignant, usually aggressive tumor composed of atypical, neoplastic melanocytes. "For instance, high levels of promoter methylation correlated with active expression of EBF3, MGMT, HOXD12 and GATA4 in melanoma, indicating other factors may affect the relations of DNA methylation with transcriptional activity." (PMID 34013637, 2021). "To test whether GATA4 pathway activation impacts response to immunotherapy, we transplanted B16 melanoma cells with the tet-Gata4 construct into immunocompetent syngeneic hosts and divided mice into control or doxycycline groups with an anti-PD-1 antibody or isotype control." (PMID 35017504, 2022).
meningioma (3 papers, 2021 to 2023). A generally slow growing tumor attached to the dura mater. "MiR-497 levels were found to be reduced in serum EVs derived from patients with high-grade compared to benign meningiomas, due to overexpression of GATA-4 in these tumors." (PMID 38001599, 2023). "The transcription factor GATA-4 was reported to be overexpressed in malignant meningiomas, where it negatively regulates the expression of miR-497-195 cluster and maintains cell viability." (PMID 38001599, 2023). "Accordingly, administration of NSC140905, a small molecule inhibitor of GATA-4 reduced expression of cyclin D1 and diminished meningioma cell viability in vitro." (PMID 35936751, 2022).
mucinous ovarian cancer (3 papers, 2009 to 2019). An invasive malignant neoplasm that arises from the ovary and is characterized by the presence of malignant epithelial cells that contain intracytoplasmic mucin and may resemble the epithelial cells of the endocervix or gastrointestinal tract. "In mucinous ovarian carcinoma, however, nuclear localisation of GATA-4 correlated negatively with the grade and stage of tumours." (PMID 19707195, 2009). "In contrast to other histological subtypes, mucinous ovarian carcinomas generally are positive for GATA4 and GATA6 expression." (PMID 19649254, 2009). "This study suggests that the expression status of GATA4 and GATA6 may dictate distinct pathologic pathways leading to serous or mucinous ovarian carcinomas." (PMID 19649254, 2009).